IL1B (interleukin 1 beta)
Diseases named in the same sentence as IL1B in open-access papers (continued):
Sharing a sentence is not in itself a finding about the gene and the disease.
tumor (continued). "The reduction of CB1 levels was more evident (to 48%) in tumor cell extracts from animals pre-treated with CBD under PS conditions, indicating that this cannabinoid promotes in the tumor cells the loss of features acquired by exposure to IL-1β." (PMID 37686042, 2023). "In IL1β deficient mice, increased secretion of IL-12 supports anti-tumor immunity and induces the activation of CD8+ T-cell which infiltrate tumors and promote regression." (PMID 37065483, 2023). "Mechanistically, tumor-associated macrophages (TAMs) activate NF-ĸB by secreting TNFα/IL-1β in the liver microenvironment and transcriptionally upregulate OTU deubiquitinase 1 (OTUD1) expression, which enhances FGL1 stability via deubiquitination." (PMID 37872170, 2023). "Although known as inflammatory factor, IL-1β can also lead to immunosuppression and IL-1β deficiency results in tumor regression." (PMID 37266440, 2023). "In tumor-associated lungs, the systemic increase in IL-1β and IL-23 induces CD27− γδ T cells to expand and rapidly produce cytokines." (PMID 36480166, 2023). "We found the loss of Il1b prolongs survival while the loss of Il1a shortens survival of tumor-bearing mice." (PMID 37733448, 2023). "IL-1β-mediated expansion of MDSCs in ccRCC tumor is also associated with elevated intratumoral levels of angiogenic IL-8, CXCL5 and chemotactic C-C motif chemokine 3 (also known as MIP-1α)." (PMID 37190141, 2023). "Macrophages, particularly tumor-associated macrophages (TAMs), are one of the main cell types that secrete high levels of IL-1β, promoting endocrine- and chemo-resistance in ER+ BC through significantly decreasing ERα levels." (PMID 37762557, 2023). "NLRP3 activates caspase-1, which then cleaves immunological and metabolic substrates, including the pro-inflammatory cytokine interleukin-1b (IL-1β), which causes inflammation and promotes tumor growth." (PMID 37715239, 2023). "Inhibition of IL-1β inhibits tumor growth and proliferation and reduces the risk of bone, lung, and other site metastasis of BC." (PMID 36765683, 2023). "IL-1b has also been implicated in promoting tumour growth by inducing neo-angiogenesis and regulating the soluble mediators that affect tumour cell survival and spreading of metastasis." (PMID 37760608, 2023). "Compared with naive MG from control mice, all tumor-associated cell types showed increased Il1b mRNA, with BMDM demonstrating the highest levels of Il1b mRNA." (PMID 37733448, 2023). "LINC01116 knockdown affects IL-1b release, which promotes the use of tumor-associated neutrophils, which, in turn, results in the accumulation of TAN, causing the production of numerous cytokines, thus leading to tumor growth." (PMID 36935487, 2023). "IL-1β also functions as a chemoattractant to recruit tumor-associated macrophages (TAMs) by attaching monocyte chemoattractant protein (MCP-1) on tumor cells." (PMID 37511306, 2023). "Two studies found that elevated plasma levels of IL-1 were significantly associated with CRF in tumor patients and IL-1β was a predictor of cancer-related fatigue during adjuvant chemotherapy." (PMID 38136423, 2023). "To demonstrate that IL-1α antagonizes the tumor-promoting effects of IL-1β, we generated tumors in WT;Ntv-a and Il1a–/–;Ntv-a: loss of Il1a resulted in accelerated tumor growth, which was the opposite of our observation in Il1b-deficient mice." (PMID 37733448, 2023). "As a result, the reduced tumor growth and activation of antitumor responses can be caused, and the protumor effects of inflammatory cytokine IL‐1β are simultaneously reduced." (PMID 37692109, 2023). "In GBM tumors, the release of IL1B by tumor-associated macrophages (TAM’s) causes gliomas to release CCL13, driving the recruitment of monocytes and their transformation into TAMs, which then drive progression." (PMID 36834607, 2023).
tumor (continued). "The inflammatory cytokines TNF-α and IL-1β are commonly found in the inflammatory environment of various tumors and are often thought to be associated with tumor promotion." (PMID 37081962, 2023). "For instance, it is known that IL-1β can favor tumor growth by inducing an immunosuppressive environment through the recruitment of myeloid-derived suppressors cells (MDSCs) and tumor-associated macrophages (TAMs), as well as by favoring angiogenesis." (PMID 37298187, 2023). "The oncological relevance of IL-1β signaling was recently demonstrated in IL1β-deficient mice, which showed inhibited tumor growth in various tumor entities and retained antitumor immunity." (PMID 37507547, 2023). "Excessive IL‐1β induces massive aggregation of MDSCs, and inhibits the activation of cytotoxic T cells, which causes a further deterioration of the anti‐tumor immune microenvironment." (PMID 37092583, 2023). "In EBV-associated NPC, increased inflammasome gene expression was associated with improved survival, and IL-1β inhibited tumor growth in a murine model of the disease." (PMID 35038917, 2022). "IL-1β production in tumors, either by tumor cells themselves or by stromal cells, is associated with a worse prognosis." (PMID 36293159, 2022). "The authors showed that tumor infiltration of neutrophils was abrogated in Il1b−/− mice, which resulted in loss of immunosuppression and restoration of anti-tumor immunity during treatment with antiangiogenic agents targeting VEGF." (PMID 35517498, 2022). "In kind, IHC of 1189 primary BCa tumor tissues showed that elevated IL-1β is positively associated with patient relapse and metastasis." (PMID 35626710, 2022). "Mutant BRAF suppresses intratumoral T cells via overexpression of IL-1α and IL-1β by tumor cells, leading to overexpression of PD-L1 and PD-L2 in tumor-associated fibroblasts." (PMID 35703181, 2022). "The authors proposed a model in which adipocyte-derived IL-1β resulted in tumor-associated neutrophil recruitment which in turn activated pancreatic stellate cells." (PMID 36074318, 2022). "NETs-associated proteinases activate matrix metalloproteinases to induce tumor-associated macrophages, which stimulate the release of pro-inflammatory factors (i.e., IL-8, IL-1β, and TNF-α), eventually leading to immune escape and tumor metastasis." (PMID 36466888, 2022). "CBD attenuates chronic inflammation by completely inhibiting the production of inflammatory cytokines by the tumor microenvironment, including IL-1β, IL-6, interferon-β (IFN-β), and TNF-α, all implicated in initiation and progression of several cancers." (PMID 35456540, 2022). "IL-1β is a pro-inflammatory cytokine, and its abnormally high expression is a predictive biomarker of tumor malignancy and increased risk of bone metastasis from breast cancer." (PMID 35701840, 2022). "It seems that the effects of IL-1β on the inhibition of anti-tumor responses are associated with its chronic activation by inflammasomes." (PMID 36293159, 2022). "After the NLRP3 inflammasome is activated, it cannot produce self-inhibition even in a resting state, which results in the continuous production of IL-1β and IL-18, finally causing long-term effects on inflammation and tumor diseases." (PMID 35292015, 2022). "We used the CD68 marker to stain the amount of tumor-associated macrophages and the IL-1β as a signal for the NLRP3 inflammasone activation." (PMID 35884397, 2022). "This is in line with multiple reports demonstrating that disruption of TNFα or IL-1R/IL-1β signaling by either blocking antibodies or deficient mouse models improves the anti-tumor immune response in combination with 5-FU or ICB." (PMID 35634282, 2022). "Fn inoculation significantly increased the expression of genes encoding the proinflammatory cytokines TNF-α and IL-1β in the tumor xenografts and colon tissues." (PMID 36551597, 2022).
tumor (continued). "SLC40A1 is highly expressed in tumor-associated macrophages, which suppresses the production of IL-1β, and is consistent with low IL-1β expression in control myeloid cells." (PMID 35962439, 2022). "The expression of IL-6, IL-8, and IL-1β is strongly associated with tumor relapse, and protects the cancer cell from chemotherapy by enhancing multidrug resistance protein 1 and antiapoptotic protein expression." (PMID 35326493, 2022). "The expression level of IL1B was significantly positively correlated with neutrophils and DCs (P < 0.001) and was significantly negatively associated with tumor purity level and macrophages (P < 0.05)." (PMID 36253777, 2022). "Tumor-derived IL-1β and constitutive IL-1 receptor-associated kinase 4 (IRAK4) activate the NF-κB signaling pathway in CAFs and pancreatic cancer cells, thereby attenuating the sensitivity to gemcitabine." (PMID 36313280, 2022). "Pro-inflammatory cytokines such as IL-1α and IL-1β are found within the HNSCC tumor microenvironment and have been linked to tumor development and spread." (PMID 36143043, 2022). "In a 2020 article, it was reported that TNF-α can be used as a prognostic indicator, while various ILs (IL-2, IL-1β, and IL-6) were also discovered to be linked to tumor prognosis." (PMID 35677632, 2022). "Elevated levels of IL-1β are associated with tumor initiation, invasiveness, and progression in a variety of malignancies." (PMID 35471938, 2022). "This is due to an early programing during cancer development of cancer-associated fibroblast, via IL-1β-secretion and nuclear factor-κB (NF-κB) activation, to sustain a tumor-promoting inflammatory response." (PMID 35328635, 2022). "Stimulation of tumor-associated macrophages (TAMs), to secrete IL-1β, and of tumor-associated neutrophils (TANs) causes metastatic progression and potentiates systemic neutrophilic inflammation." (PMID 35408994, 2022). "LMP1-mediated glycolysis enhances the production of IL-1β, IL-6, and GM-CSF, the proliferation of tumor-associated MDSCs, and the inhibition of T-cells and NK cells, which lead to tumor immunosuppression." (PMID 36303138, 2022). "High levels of IL-1β in the tumor microenvironment are associated with high proliferation and aggressive phenotype." (PMID 36499741, 2022). "The LMP1 regulates the production of IL-1β, IL-6, and GM-CSF to enhance tumor-associated MDSC expansion." (PMID 35632758, 2022). "Under HFHCD, apart from maintaining differences in neutrophils, IL-1β deficiency completely inhibited the expansion of blood monocytes and protected mice from tumor growth acceleration." (PMID 36104342, 2022). "Our previous studies show that secreted IL1β supports metastatic progression in mice by altering the transcriptome of tumor-associated bone stroma." (PMID 36561929, 2022). "The role of the inflammasome in cancer promotion is often mediated by IL-1β, which is produced by various cells in the tumor, including tumor-associated macrophages (TAMs) and cancer-associated fibroblasts (CAFs)." (PMID 35517498, 2022). "Expression of IL1B has been reported to positively correlate with tumor stages of RCC52 and is associated with worse prognosis of patients with RCC in patients recruited to TCGA." (PMID 36423636, 2022). "IL-1β inhibits tumour growth in mice, enhancing survival due to local anti-tumour immunity dependent on tumour-associated neutrophils (TANs) in the tumour microenvironment." (PMID 35998812, 2022). "In HCC, tumor-associated macrophages (TAMs) can produce cytokines to sustain tumor growth (i.e., IL-1β, TNF, IL-6), promote neo-angiogenesis via the VEGF pathway, and induce cytokine-mediated immunosuppression (i.e., IL 10, TGF-β)." (PMID 36551635, 2022). "TNF-α is the cytokine that most consistently associated with tumor cell killing through activation of the transcription factor NF-κB and subsequent production of IL-1β, IL-6, IL-8 and IL-17." (PMID 35493517, 2022).
tumor (continued). "TOGA reduced in vitro HepG2 cell migration and invasion accelerated by co-cultured tumor-associated macrophages and mitigated IL-1β-induced HepG2 NF-κB activity, a key pathway associated with tumor progression." (PMID 35335138, 2022). "Adipocyte-secreted IL-1β recruits tumor-associated neutrophils, which activate pancreatic stellate cells." (PMID 35563777, 2022). "Tumor-associated NLRP3/IL-1β signaling gives rise to an immunosuppressive environment characterized partly by the regulation of M2-polarized TAMs and a reduction in antitumor CD8+ T cells." (PMID 36376979, 2022). "NLRP3 activation in cancer cells and the consequent IL-1β secretion have been associated with transmitting signals that stimulate normal cells within the tumor microenvironment and supply them with growth factors." (PMID 34070682, 2021). "Using IL-1β -deficient mice they found that antitumor immunity was promoted by IL-12 secretion, which led to CD11b+ DC infiltration in the tumor." (PMID 33806053, 2021). "In cancer, IL1β protein is prevalent in tumor promotion in association with proinflammatory immune cells." (PMID 34135341, 2021). "In line with this, IL-1β-deficient mice transplanted with melanoma cells were protected from development of local tumor and metastases and canakinumab significantly reduced incidence of fatal cancer in the CANTOS trial." (PMID 35097027, 2021). "Through interleukin 1-Beta-mediated NF-kB signaling, these metastatic cells can drive the transformation of healthy astrocytes into tumor associated astrocytes (TAAs) that foster tumor expansion." (PMID 34899179, 2021). "The authors proposed a model where tumor‐associated macrophages secreting IL‐1β promoted GM‐CSF production by γδ T cells, leading to the maturation of CD103+CD11b– DCs, which were associated with effector CD8+ T cell infiltration within tumors." (PMID 33188652, 2021). "In line with this notion, the dysregulation of inflammasome signaling and/or consequent reduction of IL-1β and IL-18 production were associated with tumor growth and metastasis in colorectal cancer." (PMID 34490126, 2021). "Considering the agonist role of IL-1β on MDSCs (24, –26) and the role of these cells in tumor-associated immunosuppression, we assessed the effect of NLRP3 inhibition on MDSCs." (PMID 33649199, 2021). "GRO-α, IL-1β, Oncostatin-M and Leptin, all linked to tumor growth and inflammation, were significantly altered in the IORT group: Leptin increased; GRO-α, IL-1β, oncostatin-M decreased." (PMID 33946741, 2021). "In oral squamous cell carcinoma cell lines, NLRP3 inflammasome activation and IL-1β secretion were associated with tumor progression, metastases and infiltration of immune suppressive myeloid cells, such as TAMs and MDSCs into the TME." (PMID 33572196, 2021). "CXCL13 and IL1B are both implicated in both cancer metastasis and recruitment of immune cell populations to tumor cells, particularly B cells and macrophages." (PMID 33888854, 2021). "RT-PCR analysis revealed that these tumor-infiltrating macrophages expressed higher levels of transcripts encoding IL-1β, IL-12, IL-23, and TNF-α in the AAA-CD4+ group than in the control or auto-CD4+ groups." (PMID 34625113, 2021). "In metastatic melanoma, tumor-associated NLRP3/IL-1β signaling induced expansion of MDSCs, leading to reduced NK and CD8+ T-cell activity concomitant with an increased presence of Treg cells in the primary tumors." (PMID 35003065, 2021). "The nude mouse xenograft tumor model was used to further validate the KRAS mutation-dependent PDAC tumor growth promoted by IL-1β, TNF-α, and Shh stimulation." (PMID 34046348, 2021).
tumor (continued). "Tumor necrosis factor-alpha (TNF-α) and interleukin-1 beta (IL-1β) produced by inflamed immune cells such as tumor-associated macrophages (TAMs) promote the expression of inflammatory molecules in other cell types." (PMID 34084145, 2021). "IL-1β-deficient tumor-bearing mice were shown to have lower levels of CCL2 in tumor tissue, which resulted in decreased macrophage infiltration and CD11b+ dendritic cell maturation." (PMID 34386431, 2021). "For example, ARG1 and IL-1β were found to be enriched in both tumor-associated microglia and macrophages." (PMID 33766119, 2021). "For instance, in breast cancer, IL-1β production promotes the infiltration of myeloid-derived suppressor cells (MDSCs) and tumor-associated macrophages (TAMs), providing an inflammatory microenvironment and favoring tumor progression." (PMID 35008212, 2021). "In this context, proinflammatory cytokine response genes CSF-1 and IL1b induced in prostate epithelial cells cause tumor development via MDSC expansion that further leads to immune suppression." (PMID 35011582, 2021). "Functionally, B cells recruited into renal tumors have been implicated in promoting tumor migration and metastatic potential via IL-1β/HIF-2α signaling." (PMID 34831452, 2021). "A single injection of IL-1β compensated for the effect of ROS deficiency on tumor colonization, increasing tumor colonies to a high level." (PMID 34257370, 2021). "Inflammatory cytokines, including TNF-α and IL-1b, can induce tumour-associated macrophages and endothelial cells to express TF." (PMID 34326419, 2021). "Along these lines, Kaplanov and colleagues noticed that the neutralization of IL-1β was associated with tumor regression." (PMID 33806053, 2021). "Interaction of IL-1β with the TME leads to monocyte recruitment that then differentiate into tumor-associated macrophages (TAMs) whose increased levels in HNSCC are associated with poor prognosis." (PMID 35048046, 2021). "Overexpression of IFI16 in tumor cells activated inflammasome machinery, thereby inducing the production of IL-1β and causing maturation, proliferation, and migration of TAMs in the tumor microenvironment." (PMID 34150748, 2021). "Inflammation-associated enhancement of IL-1β exerts immunosuppressive effects in tumor microenvironment and supports tumor progression and metastatic processes in many different human malignancies." (PMID 34070682, 2021). "In IL-1β deficient mice and using IL-1RA in wild type, an antagonist for IL-1β, the vascularization of the tumor was abrogated." (PMID 34055597, 2021). "Cancer cells also drive tumor-associated inflammatory macrophages to produce IL-1β, which inhibits tumor immune response through IL-1β-mediated accumulation of myeloid derived suppressor cells (MDSCs)." (PMID 34386015, 2021). "In tumor-bearing mice, its deficiency leads to increased activation of caspase-1 and IL-1β production by DCs." (PMID 32635472, 2020). "The higher expression of interleukin IL-1β and IL-4 delineated a high-risk association with bone metastasis and tumor progression." (PMID 33112542, 2020). "IL‐1ra competitively blocks the pro‐inflammatory actions of IL‐1α and IL‐1β at the receptor level, which have been implicated in tumor growth." (PMID 33207085, 2020). "In an azoxymethane (AOM)/ dextran sodium sulfate (DSS)-induced cancer-associated colitis model, complement deficiency was shown to inhibit intestinal IL-1β production by neutrophils and IL-17A production by myeloid cells, and to repress tumor formation." (PMID 32635472, 2020). "Oncogenic BRAF, through decreased MITF expression and enhanced IL-1α and IL-1β secretion, triggers PD-L1 and PD-L2 expression in tumor-associated fibroblasts which also contributes to suppression of tumor-infiltrating T cell function." (PMID 33276788, 2020).